CHI3L1 (chitinase 3 like 1)
Diseases named in the same sentence as CHI3L1 in open-access papers (continued):
Sharing a sentence is not in itself a finding about the gene and the disease.
asthma (continued). "In the total population we found an adjusted association between homozygosity of the rs4950928 G allele (minor allele) of CHI3L1 and self-reported physician diagnosed asthma." (PMID 19568425, 2009). "However, the criterias for the asthma diagnosis used in the present study are similar to the ones used in previous studies on the effects of variation in CHI3L1 on asthma." (PMID 19568425, 2009). "However, a role for YKL-40 (CHI3L1) during type 2 inflammatory disease cannot be ruled out as it has been reported to be elevated in the serum of asthmatics and associated with increased asthma severity." (PMID 41159038, 2025). "However, results are conflicting as to whether CHI3L1 serves as a specific biomarker for type 2 (T2) asthma." (PMID 41154593, 2025). "Notably increased YKL-40 protein levels have been reported in the serum in people with certain asthma endotypes and genome wide association studies have highlighted CHI3L1 as a risk gene for asthma." (PMID 40996619, 2025). "Thus, the inhibition of CHI3L1 or CHI3L1 pathways could provide potential therapeutic treatments for obesity-related asthma." (PMID 38667293, 2024). "For example, adenovirus vector-mediated Chi3l1 shRNA can downregulate Chi3l1 levels and alleviate eosinophilic airway inflammation, airway hyperresponsiveness, and airway mucus secretion in an asthmatic mouse model, which highlights treatment prospects for human asthma." (PMID 39769202, 2024). "A recent review has compiled data describing that individuals with asthma may be predisposed to features of airway remodeling based on single nucleotide polymorphisms in remodeling-associated genes, including IL13, PLAUR, VEGFA, and CHI3L1." (PMID 37773065, 2023). "Other CHI3L1 polymorphisms may play a role in development of asthma and are distinctly related to steroid-insensitive, non-T-helper cell type 2 chronic inflammation." (PMID 30940096, 2019). "Therefore, the larger number of atopic individuals in the Tsukuba replication cohort compared with the Tsukuba GWAS and Hokkaido replication cohorts may obscure the role of CHI3L1 in the development of asthma in the Tsukuba replication population." (PMID 30940096, 2019). "In addition, higher Chi3l1 levels (168 ± 71.5 ng/mL) were associated with obesity-related asthma than with early-onset atopic and late-onset non-atopic phenotypes (80.62 ± 46.9 and 51.5 ± 24.9 ng/mL, respectively)." (PMID 28696379, 2017). "To date, the effect of genetic variation in CHI3L1 on asthma risk has not been fully addressed." (PMID 29233108, 2017). "In this prospective cohort study we found no robust association between genetic variation in CHI3L1 and asthma development, but found some indication that rs10399805 might be related to asthma diagnosis at 6 years." (PMID 27193312, 2016). "Genetic variation in CHI3L1 might be related to the development of milder forms of asthma." (PMID 27193312, 2016). "Moreover, rs10399805 and rs2275353 in CHI3L1 were found be significantly associated with atopy but not asthma in a Korean population." (PMID 25056157, 2014). "Thus, more studies seem warranted to establish the role of CHI3L1 gene in asthma and atopy." (PMID 19568425, 2009). "In conclusion, NOS2, TCN1, CHI3L1 and TIMP1, as key immune and inflammatory regulatory targets, play an important role in the comorbidity of asthma and ulcerative colitis." (PMID 40443529, 2025). "Our findings support previous evidence indicating altered expression of CHI3L1 and PI3 in asthma, particularly at the gene level." (PMID 41154593, 2025). "Asthma data results show that NOS2 is resting with Mast cells (R = 0.26, p = 0.014), TIMP1 is resting with Plasma cells (R = 0.27, p = 0.011), CHI3L1 is resting with Neutrophils (R = 0.38, p = 0.00029) is positively correlated." (PMID 40443529, 2025). "Then, the genes selected by the two methods were crossed, and finally, the key genes involved in the progression of asthma to UC (CXCL13, NOS2, TCN1, CHI3L1 and TIMP1) were obtained." (PMID 40443529, 2025).
asthma (continued). "Previously, we defined CHI3L1 and PI3 as genes related with asthma and severity by analysis of differential gene expression." (PMID 41154593, 2025). "This study highlights NOS2, TCN1, CHI3L1, and TIMP1 as potential biomarkers and therapeutic targets for asthma and UC, providing insights into shared mechanisms and new strategies for diagnosis and treatment." (PMID 40443529, 2025). "GSEA analysis showed that NOS2, TCN1, CHI3L1 and TIMP1 were jointly involved in cytokine receptor interaction in asthma and ulcerative colitis chemokine signaling pathway." (PMID 40443529, 2025). "In this study, we aim to further validate the utility of CHI3L1 and PI3 expression as asthma biomarkers and explore the role of DNA methylation as an epigenetic modulator involved in their regulation." (PMID 41154593, 2025). "The results showed that only four genes (NOS2, TCN1, CHI3L1, TIMP1) showed statistically significant differences in expression in the data sets validated by asthma and UC compared with the control group." (PMID 40443529, 2025). "Chitinase-3-like protein 1 (CHI3L1) is a secreted glycoprotein that is induced and regulated by multiple factors during inflammation in enteritis, pneumonia, asthma, arthritis, and other diseases." (PMID 39068486, 2024). "Several studies have shown that CHI3L1(YKL40) is upregulated in various diseases, such as cancer, asthma, and inflammatory bowel disease, among others." (PMID 38543093, 2024). "Previously reported overexpressed (IL-10, MSR1, PHLDA1, SERPINB2, and CD86) and underexpressed genes (CHI3L1, CPA3, IL-8, and PI3) in severe asthma were analyzed by RT-qPCR in peripheral blood mononuclear cells (PBMCs)." (PMID 37445432, 2023). "Studies of human allergic diseases reveal that expression of YKL-40 protein and CHI3L1 transcripts are increased in the lungs and serum of some asthma cohorts." (PMID 37575256, 2023). "HHIP and CHI3L1 were both over-expressed in CF as well as in chronic obstructive pulmonary disease (COPD) and asthma." (PMID 32492951, 2020). "A high number of positive correlations between the assessed cytokines and CHI3L1, IL-12p40, IL-1β, IL-6, IL-8, TNF in moDCs was observed in asthma and COPD." (PMID 32842623, 2020). "Briefly, the combinations of IL-10 and POSTN, CHI3L1 with IL-10 and POSTN, or CHI3L1 with IL-8 and POSTN are proposed as good or very good sets of biomarkers to differentiate between the two types of asthma." (PMID 31143187, 2019). "When two biomarkers were combined, the combinations of CHI3L1 + POSTN, IL10 + POSTN, IL-8 + PI3, and SERPINB2 + POSTN were good to discriminate severe from moderate–mild asthma, and of smaller importance was the grouping of IL-8 + POSTN." (PMID 29977241, 2018). "Chitinase-3-like-1 (Chi3l1, YKL-40) a glycoprotein member of the glycosyl hydrolase 18 family, has been shown to play an important role in asthma-obesity development." (PMID 28696379, 2017). "Among the top genes are ones that have been previously related to asthma (e.g., APOE, CHI3L1, EGR1, MYH11, OXTR, SERPINB2, SOCS3) and corticosteroid-resistant asthma (e.g., FOS) though not necessarily in humans or via changes of the ASM." (PMID 26207385, 2015). "Overall, the study does not consistently present specific variations of CHI3L1 that are associated with both clinical informations and symptoms of asthma and/or atopy as well as measures of lung function but the study does not exclude a potential role of CHI3L1 in susceptibility to asthma." (PMID 19568425, 2009). "In conclusion, CHI3L1 and PI3 represent potential asthma biomarkers, whose regulation may be partially influenced by DNA methylation, a mechanism more pronounced in asthmatic patients than in healthy subjects." (PMID 41154593, 2025). "Chi3l1 potentially promotes bronchial smooth muscle proliferation and migration by inducing IL-8 expression in the bronchial epithelium via the MAPK and NF-κB pathways in asthma." (PMID 39769202, 2024).
asthma (continued). "Nevertheless, we are unable to determine if the effect of genetic variation of CHI3L1 on current asthma is reflected by current YKL-40 levels, as YKL-40 levels were not measured at 6 years." (PMID 27193312, 2016). "In this large study of well-characterised Danish patients with mild to severe asthma, we found that patients with the CHI3L1 (131 CC, rs4950928) genotype had higher serum concentrations of YKL-40 compared with patients with the CHI3L1 (−131 GG, rs4950928) genotype." (PMID 26672955, 2015). "In contrast to previous studies of variations in CHI3L1 in relation to asthma, limitations of the present study are the lack of measurements of serum YKL-40." (PMID 19568425, 2009). "Chitinases, chitotriosidase (CHIT1), acidic mammalian chitinase (AMCase or CHIA), and nonenzymatic chitinase-3-like protein 1 (CHI3L1) have been implicated in various pathological conditions, such as Gaucher’s disease (CHIT1), obesity, diabetes, cardiovascular diseases, and asthma (CHIA)." (PMID 35330193, 2022). "Interestingly, TSLP expression in moDCs from triple co-culture correlated positively with IL12p40, IL-6, and TNF-α in asthma, whereas in COPD with CHI3L1, IL12p40, IL-6, IL-8, TNF-α, and IL-1β suggesting a different pathway of immune response in asthma and COPD." (PMID 32842623, 2020). "A recent study showed that Th2-mediated inflammation and high-fat-diet–induced expression of chitinase 3-like 1 (a chitinase-like protein, also called YKL-40 in humans and breast regression protein-39 in rodents) simultaneously contribute to the genesis of both obesity and asthma." (PMID 31192262, 2019). "YKL-40 is also called chitinase-3-like-1 (CHI3L1) protein and may be a marker for asthma." (PMID 25578181, 2015). "All together, it seems that genetic variations in CHI3L1 could account for inter-individual YKL-40 levels and that YKL-40 in asthma, sarcoidosis and COPD and plays a part of the pathogenesis with a role of acute inflammatory as well as chronic fibrotic character." (PMID 19568425, 2009). "In conclusion, our results support CHI3L1 and PI3 as gene biomarkers for allergic and nonallergic asthma." (PMID 41154593, 2025). "Chi3l1 is reported to be a non-type 2 inflammatory signature for non-eosinophilic asthma (NEA), which is correlated with inflammatory phenotypes, anti-asthma responsiveness, and future exacerbations." (PMID 39769202, 2024). "MUC5B, ORMDL3, MUC5AC, CHI3L1, CLCA1, and IL-33 displayed a high non-specific relationship with allergic and nonallergic asthma." (PMID 33936056, 2021). "New genes and protein biomarkers, including CHI3L1, IL-8, IL-10, MSR1, PHLDA1, PI3, and SERPINB2, were proposed to discriminate healthy control subjects from non-allergic asthmatic patients (T2-low) and to determine asthma severity." (PMID 33936056, 2021). "In a recent work, new gene and protein biomarkers CHI3L1, IL-8, IL-10, MSR1, PHLDA1, PI3, and SERPINB2, were proposed to discriminate healthy control subjects from nonallergic asthmatic patients (T2-low) and to measure asthma severity." (PMID 31143187, 2019). "It has never been addressed whether SNPs in CHI3L1 and cord blood YKL-40 levels could already serve as potential biomarkers for milder forms of asthma." (PMID 27193312, 2016).
glioblastoma (116 papers, 2007 to 2026). The most malignant astrocytic tumor (WHO grade IV). "Orthogonal structure screening for membrane-associated binding proteins of CHI3L1 in glioblastoma predicted that Gal3BP, encoded by LGALS3BP, competes with Gal-3 for the same binding site on CHI3L1." (PMID 39068486, 2024). "CHI3L1, a secreted protein, in glioblastoma and its association with radiation response and prognosis." (PMID 39033204, 2024). "Overexpression of CHI3L1 is associated with a poor prognosis in glioblastoma patients, and it is involved in cancer cell growth, proliferation, invasion, metastasis, and angiogenesis." (PMID 37091145, 2023). "CHI3L1 has been recently reported to modulate M2-like phenotype of tumor-associated macrophages, which contributes to immune suppression in glioblastoma." (PMID 34612767, 2021). "Astrocytic co-culture as well as CHI3L1 treatment causes a transcriptional shift of glioblastoma cells towards a mesenchymal phenotype followed by increased proliferation and migration." (PMID 31561550, 2019). "Chitinase-3-like protein 1 (CHI3L1), a member of the chitinase family, has been implicated in several cancers, such as glioblastoma, breast cancer, and ovarian cancer." (PMID 31238895, 2019). "A recent meta-analysis of 1241 glioblastoma patients confirmed our results by showing that high CHI3L1 expression was associated with poor prognosis (HR = 1.46; 95% CI, 1.33–1.61; p < 0.001)." (PMID 30991699, 2019). "CHI3L1 overexpression was associated with mesenchymal subtype in glioblastoma (defined by IDH wild-type)." (PMID 30991699, 2019). "Consistent with a role of CD44, MMP9 and CHI3L1 in aggressive glioblastoma properties, low expression of the three genes was associated with better outcome in TCGA samples." (PMID 28036297, 2017). "Elevated CHI3L1 levels in the bloodstream are linked to more aggressive tumor behavior, reduced effectiveness of standard therapies, and shorter survival times, offering a clearer yet concerning view of glioblastoma progression." (PMID 39827337, 2025). "CHI3L1 expression is positively associated with increased angiogenesis and metastasis in highly malignant tumors such as colorectal cancer, lung cancer, and glioblastoma." (PMID 38667293, 2024). "Additionally, CHI3L1 expression was significantly associated with genetic abnormalities in glioblastomas, specifically loss at chromosome 10q." (PMID 39033204, 2024). "Also, CHI3L1 is highly expressed and associated with a poor clinical outcome in glioblastoma patients." (PMID 39768176, 2024). "A previous study showed that increased mRNA level of CHI3L1 could be associated with poor patient survival for glioblastoma and lower-grade astrocytoma tumors." (PMID 36091778, 2022). "A transcriptional shift of glioblastoma cells towards a mesenchymal phenotype followed by increased proliferation and migration is partially caused by a glycoprotein Chitinase 3-like 1 (CHI3L1, also termed YLK-40) released by tumor-associated reactive astrocytes." (PMID 34949203, 2021). "Since a recent study demonstrated that CHI3L1 is less expressed in IDH-mutated glioblastoma, we determined whether IDH status was connected with other independent molecular factors by multivariate analysis." (PMID 30991699, 2019). "Findings presented in our study showed that increased mRNA level of CHI3L1 could be associated with the progression of astrocytoma and poor patient survival not only for glioblastoma, but for lower grade astrocytoma tumors as well." (PMID 27121858, 2016). "Findings presented in our study showed that the increased mRNA level of CHI3L1 could be associated with the progression of astrocytoma and with poor patient survival not only in the glioblastoma but in the lower grade astrocytoma tumors as well." (PMID 27121858, 2016). "Induction of autophagy in glioblastoma cells after CHI3L1 inhibition was observed, as well changes in CHI3L1 expression levels occurred after cell starvation and different X-ray radiation doses." (PMID 42062601, 2026).
glioblastoma (continued). "In glioblastoma, the TME-derived glycoprotein chitinase-3-like protein 1 (CHI3L1), in association with Gal3, promotes M2 polarization, resulting in reduced CD4+ and CD8+ T cell populations." (PMID 41019045, 2025). "In contrast, a negative strong significant Spearman correlation (R=-0.69, p = 0.0014) was observed for glioblastoma spheroids, indicating that CHI3L1 inhibition resulted in a reduction in CDH2 mRNA levels." (PMID 39607670, 2025). "In studies on glioblastoma, CHI3L1 has been found to stimulate angiogenesis by inducing a coordinated interaction between syndecan-1 and integrin αvβ5 on the surface of glioma cells." (PMID 39068486, 2024). "The CHI3L1 expression seems to alter the state of GSCs to support tumor growth and regulate cellular plasticity, leading to a targetable vulnerability to glioblastoma." (PMID 38667293, 2024). "Elevated levels of CHI3L1 are a common feature in various cancers, including breast, lung, ovarian cancer and glioblastoma, as well as in inflammatory diseases such as multiple sclerosis (MS), Alzheimer’s, Parkinson’s and asthma." (PMID 39399677, 2024). "The strategy of blocking CHI3L1 with specific antibodies has been used in mouse models to decrease progression of melanoma, glioblastoma, lung, pancreatic, colon and breast cancer." (PMID 38605414, 2024). "iPSCs and NSCs have significantly improved the study of genetic alterations in glioblastoma, highlighting the roles of PTEN deficiency and CHI3L1 expression in tumor development and aiding in therapeutic strategy formulation." (PMID 39768176, 2024). "IHC reactions showed expression of markers characteristic of three cell types that form the spheroids: CHI3L1-positive U-87 MG glioblastoma cells, CD31-positive endothelial cells (HMEC-1) and IBA1 markers for macrophages." (PMID 39399677, 2024). "CHI3L1, a gene encoding YKL-40, is a marker of the glioblastoma mesenchymal subtype and is overexpressed in glioblastoma tumor stem cells." (PMID 37887529, 2023). "CHI3L1 is produced by various cells and overexpressed in many human cancer types and animal tumor models, such as oligodendroglioma and glioblastoma." (PMID 37887529, 2023). "In this study, we analyzed the expression, prognosis, and survival curves of EMP3 and CHI3L1 in low-grade glioma and glioblastoma." (PMID 37887529, 2023). "The roles of CHI3L1 in glioma survival, proliferation and invasion were further investigated in four glioblastoma (GBM) cell lines and in vivo animal experiments." (PMID 36276655, 2022). "Conversely, mesenchymal subtype glioblastomas were characterized by high expression of chitinase 3 like 1 (CHI3L1) and tyrosine-protein kinase Met (MET), a high frequency of neurofibromin 1 (NF1) mutation/deletion, and low NF1 gene expression." (PMID 36591531, 2022). "Pro-angiogenic and metastatic activity of CHI3L1 has been efficiently blocked in vitro and in vivo in an animal model of glioblastoma multiforme by neutralizing antibody treatment, highlighting the potential benefit of this approach." (PMID 34949203, 2021). "Its homologous gene, CHI3L1, has been extensively studied in various tumors and has been shown to be related to immune infiltration in breast cancer and glioblastoma." (PMID 33937022, 2021). "Recently, chitinase 3 like 1 (Chi3L1) expression has been found in a variety of cancer cells such as breast, lung, prostate, colon, rectum, ovary, kidney, glioblastomas, and malignant melanoma 14-20." (PMID 31929760, 2020). "CHI3L1, a gene encoding YKL-40, a marker of the glioblastoma mesenchymal subtype, is overexpressed in glioblastoma cancer stem cells." (PMID 30991699, 2019). "CHI3L1 is overexpressed in both serum and tumor tissue from a variety of human tumor types, such as glioblastoma, breast cancer, melanoma, gastric and colorectal cancer, for which it has been proposed as both a biomarker and potential therapeutic target." (PMID 30165890, 2018).